BDNF (brain derived neurotrophic factor)
Diseases named in the same sentence as BDNF in open-access papers (continued):
Sharing a sentence is not in itself a finding about the gene and the disease.
mood disorder (continued). "In addition to the comparison between the blood level of BDNF in mood disorder patients and healthy controls, several studies further investigate the effect of different disorder statuses." (PMID 26091093, 2015). "Research on peripheral BDNF was originally driven by the aim of better understanding the pathophysiology of mood disorders; however, in the last few years, BDNF has been attracting attention as a potential biomarker capable of advancing the elusive field of personalised medicine in psychiatry." (PMID 26621529, 2015). "Considering the biological process from the gene level to different protein products might be necessary in studying BDNF and its phenotypes, including mood disorders." (PMID 26091093, 2015). "We found that BDNF mRNA level was neither associated with mood disorders nor exhibited substantial fold change between mood disorder patients and healthy controls." (PMID 26091093, 2015). "Therefore, it is preferable to consider an integrative framework to accommodate a large amount of genomic data from different sources rather than focusing on one specific study design to weight the influences of BDNF in mood disorders." (PMID 26091093, 2015). "In addition, this evidence also supports the involvement of both pro-BDNF and m-BDNF in the etiological mechanisms of mood disorders." (PMID 26091093, 2015). "Thus, it is essential to adopt strategies from systems biology and to incorporate PPI information and pathway analysis to enhance our understanding of the roles of BDNF in mood disorders." (PMID 26091093, 2015). "A data integration strategy is necessary to evaluate the role of BDNF in mood disorders." (PMID 26091093, 2015). "In contrast to genomic studies that investigate the relationship between gene and mood disorders, the protein level of BDNF seemed to be closer to behavioral expression and may have a more direct effect on mood disturbances." (PMID 26091093, 2015). "Examining the changes in pro-BDNF and m-BDNF blood levels and the pro-BDNF/m-BDNF ratio may be useful and important for the early detection of mood disorders." (PMID 26091093, 2015). "Ethanol extract of Yueju pill, a Traditional Chinese Medicine herbal formula widely used to treat mood disorders, demonstrates rapid antidepressant effects similar to ketamine, likely via instant enhancement of brain-derived neurotrophic factor (BDNF) expression in the hippocampus." (PMID 25878718, 2015). "Brain-derived neurotrophic factor (BDNF) plays important roles in neuronal survival and differentiation; however, the effects of BDNF on mood disorders remain unclear." (PMID 26091093, 2015). "In addition, the factors and contributors that lead to the cleavage of pro-BDNF to m-BDNF are also key points in understanding the mechanism of mood disorders." (PMID 26091093, 2015). "Individuals endowed with at-risk alleles of the BDNF gene may have compromised ability to normalize HPA axis activity, thereby adding to mood-disorder pathology." (PMID 25202283, 2014). "The hypothesis of neuronal plasticity involved in mood disorders has been supported by the use of antidepressants and mood stabilizers, e.g. lithium and valproate, inducing the expression of neurotrophins (e.g. BDNF) and synaptic changes." (PMID 25539739, 2014). "In addition to the well-known functions of BDNF acting as a neurotrophin, several studies involving human subjects and animal models provide preliminary data supporting a role for BDNF also in stress and mood disorders." (PMID 24146812, 2013). "We explored the hypothesis that BDNF expression is controlled by balancing the activity of BDNF promoter IV (BP4) with a negative regulatory region containing a polymorphism associated with cognitive dysfunction and mood disorders." (PMID 22265241, 2012). "A growing body of evidence demonstrated that chronic stress decreases the expression of BDNF in limbic structures in the central nervous system, which may contribute to mood disorder." (PMID 23284991, 2012).
mood disorder (continued). "There is indication that α-Syn may regulate expression of the brain-derived neurotropic factor (BDNF) which plays an important role in the mood disorders." (PMID 21124898, 2010). "Together, these findings highlight the critical role of BDNF-TrkB signaling in mediating antidepressant effects and suggest that dietary compounds capable of modulating this pathway, such as green tea, warrant further investigation in the treatment of mood disorders." (PMID 40722728, 2025). "Incorporating lifestyle interventions, particularly regular physical activity, may be an effective strategy for restoring BDNF levels, counteracting stress-induced neuronal atrophy, and mitigating the inflammatory and mitochondrial dysfunction pathways contributing to mood disorder pathophysiology." (PMID 40244068, 2025). "Thus, increased BDNF synthesis could be a characteristic of acute episodes of mood disorders, although the literature is unclear." (PMID 39170712, 2024). "Over the years, increasing evidence demonstrated the role of BDNF in the pathophysiology of stress-related disorders as well as in the context of the complex relationships between stressful life events, acute or chronic, and the onset or exacerbation of mood disorders." (PMID 38542503, 2024). "Additionally, controlling for potential confounders such as lifestyle factors and medication use and including a broader range of clinical populations with comorbid conditions would provide a more comprehensive understanding of the roles of BDNF and serotonin in mood disorders." (PMID 39493096, 2024). "Polymorphism in some single nucleotide polymorphism (SNP)s, such as brain-derived neurotrophic factor (BDNF) Val66Met, or catechol-O-methyl transferase (COMT) Val158Met have turned out to be associated with varying outcomes with tDCS application in cognitive and mood disorder." (PMID 35330487, 2022). "Moreover, peripheral BDNF levels appear to be decreased in stress-related mood disorders and reduced BDNF expression may be involved in their pathogenesis." (PMID 35250657, 2022). "Definitive conclusions regarding the role different transcripts play in BDNF signaling are still lacking, but it is of great interest giving that BDNF mRNA variants are differently (down)regulated in individuals suffering from neuropsychiatric disorders, including mood disorders." (PMID 34068707, 2021). "BDNF genotype and expression can be expected to modulate BDNF levels and/or its neuroplastic effects and may, therefore, affect the vulnerability to develop mood disorders." (PMID 32116853, 2020). "However, the potential mechanism of BDNF action in the neuroimmune axis' regulation of mood disorders remains unclear." (PMID 31231295, 2019). "Finally, further studies are essential to elucidate the molecular involvement of cAMP signaling in p11 and BDNF dependent regulation of proliferation of NPCs upon ketamine treatment, as both are suggested to play an important role in mood disorders and neurogenesis." (PMID 31554266, 2019). "There is also evidence that the lack of BDNF is linked to the pathophysiology of mood disorders." (PMID 29364170, 2018). "Thus, exploration of the relationships between BDNF and mood disorders could benefit substantially from a systematic review of the currently available evidence from different study designs." (PMID 26091093, 2015). "The significant findings in our pathway analysis (especially when we considered the I-genes) suggest that the association of BDNF with mood disorders may not be through the main effect." (PMID 26091093, 2015). "However, the hypothesis that the impairment of the BDNF/TrkB pathway alone can lead to mood disorder is still a matter of debate." (PMID 24795586, 2014). "Therefore, it is possible that genetically altered rats might produce more consistent results than mice when attempting to assess the role of BDNF in mood disorders." (PMID 24817844, 2014).
mood disorder (continued). "Taken together, our present study, when examined in the light of these previous observations, is consistent with the hypothesis that the C allele reduces BDNF expression level by reducing BP4 activity to neuron activation, thus contributing to susceptibility to mood disorders." (PMID 22265241, 2012). "Lactobacillus rhamnosus (strains zz-1, UBLR-58, and JB-1) and Bifidobacterium longum complete the list of microorganisms with a documented effect on mood disorders, acting through regulation of the HPA axis and modulation of signaling pathways related to BDNF." (PMID 40647242, 2025). "Mood disorders like major depressive disorder (MDD) and bipolar disorder (BD) involve complex interactions between brain-derived neurotrophic factor (BDNF) and serotonin." (PMID 39493096, 2024). "This elevation in BDNF supports synaptic plasticity, neuronal health, and mood regulation, linking SSRI use to improvements in mood disorder symptoms." (PMID 39493096, 2024). "Publications in the cluster focused mainly on brain-derived neurotrophic factor (BDNF) gene and on its role in the pathogenesys of mood disorders." (PMID 36833279, 2023). "In addition, research containing measures of oxidative stress, BDNF regulation, or other physiological markers would be informative alongside mood measurement to investigate the mechanistic potential of flavonoids as therapeutic agents in reducing or preventing mood disorders." (PMID 34371893, 2021). "Altogether this implicates BDNF as a potential biomarker for MDD, but also for other mood disorders." (PMID 34298958, 2021). "Recently, a correlation between the dysregulation of brain-derived neurotrophic factor (BDNF) in the CNS and mood disorders has been reported." (PMID 32560413, 2020). "It would be of great interest to investigate BDNF, CAM, and anhedonia levels in a sample of patients with only mood disorders in further research." (PMID 32372985, 2020). "Sodium butyrate administration also exerts an antidepressant effect related to the increased expression of brain-derived-neurotrophic factor (BDNF), which is diminished in mood disorders." (PMID 29615850, 2018). "Mean serum BDNF levels at follow-up in cases that had not been treated with any antidepressant but had fulfilled the diagnostic criteria of current episodes for each mood disorder were 7.3 (s.d.=3.7) ng ml−1 for MDD, 12.8 (5.9) for minDD and 6.8 (4.2) for minDE with MDE history." (PMID 27070410, 2016). "In cultured microglia, morphine upregulates brain-derived neurotrophic factor (BDNF), which is known to act on the NMDA receptors and influences mood disorders." (PMID 27148260, 2016). "Thus, the results from linkage studies provided negative evidence for mutations of the BDNF gene to have any direct and substantial effect on the familial inheritance of mood disorders, which may be due to the complex genetic etiology underlying MDD and BPD." (PMID 26091093, 2015). "The presence of these new interventions reinforces the role of BDNF for mood disorders, especially in those patients who do not respond to treatment in the traditional manner." (PMID 40362507, 2025). "Additionally, P2X7R directly regulates hippocampal glutamate release and influences the brain-derived neurotrophic factor (BDNF) signalling pathway, which are crucial for neuronal plasticity and are often disrupted in mood disorders." (PMID 40429831, 2025). "The correlation coefficient between BDNF levels and mood disorder severity was -0.32, indicating a significant negative correlation (p = 0.045)." (PMID 39493096, 2024). "A significant negative correlation between BDNF levels and mood disorder severity (r = -0.32, p = 0.045) suggests that reduced BDNF levels are associated with more severe symptoms." (PMID 39493096, 2024).
mood disorder (continued). "Furthermore, changes in hippocampal homeostasis, including neuroinflammation, oxidative stress, imbalance in neurotransmitter levels, and decrease in brain-derived neurotrophic factor (BDNF), are key to the evolution of mood disorders in diabetic patients." (PMID 37892186, 2023). "Similarly, neuronal cell-related growth factors BDNF and GDNF are also considered to play crucial roles in the fluctuations in neurotransmitters in mood disorders." (PMID 40224600, 2023). "P-CREB, BDNF, and PSD-95 decreased in the ACC, while CREB did not change, so that 666–15 suppresses upward transmission of pain signals in the spinal cord, blocks activation of the CREB/BDNF signaling pathway in the ACC, and prevents the progress of mood disorders." (PMID 35401106, 2022). "It should also be mentioned that BDNF and VEGF could play a synergistic role in the complex of mood disorders." (PMID 32849818, 2020). "Numerous studies reported reduced BDNF and NGF levels in patients with mood disorders." (PMID 28550529, 2018). "We investigated whether serum BDNF levels decrease before or after the developments of MDD and other mood disorders through a case–control study nested in a cohort of 1276 women aged 75–84 years in 2008." (PMID 27070410, 2016). "Although not statistically significant, BDNF levels at baseline seemed higher in the mood disorders groups than in the control group." (PMID 27070410, 2016). "Although BDNF has been widely tested for mood disorders, the evidence was not consistent across different study designs and individual studies." (PMID 26091093, 2015). "Associations between BDNF and mood disorders were not significant in most of the genomic studies (e.g., linkage, association, gene expression, GWA), while relationships between serum/plasma BDNF level and mood disorders were consistently reported." (PMID 26091093, 2015). "Carriers of the minor BDNF and ANK3 alleles showed nonsignificant trends toward protective association in controls relative to mood disorder patients (P = 0.047)." (PMID 24944871, 2014). "Thus, there may not be any direct association between BDNF and mood disorders." (PMID 24817844, 2014). "Therefore, the present study was geared toward determining: 1) the rates of mood disorders and its relationship with HAU, and 2) to assess the impact of Brain Derived Neurotrophic Factor (BDNF), a well-known regulator of alcohol and mood disorders." (PMID 26501066, 2014). "Previous studies have shown that BDNF levels are not stable in people with mood disorders." (PMID 37009109, 2023). "According to the neurodevelopmental and neuroimmunological hypotheses of mood disorders, we analyzed serum levels of brain-derived neurotrophic factor (BDNF), proBDNF, epidermal growth factor (EGF), migration inhibitory factor (MIF), stem cell factor (SCF), and correlations with clinical factors." (PMID 34575175, 2021). "However, the peripheral increase in growth factors (BDNF and NGF) and inflammatory cytokines initiated by nerve damage may be involved in the pathophysiology of mood disorders as they are related to pain." (PMID 34589875, 2020). "To summarize, we observed a general pattern that most linkage and GWA association studies provided negative findings for BDNF with mood disorders, while studies examining serum/plasma levels of BDNF provided more consistent positive findings for its involvement in mood disorders." (PMID 26091093, 2015). "To investigate whether serum BDNF levels decease before or after the development of MDD and other mood disorders, we longitudinally examined serum BDNF levels in cases and controls of mood disorders derived from a population cohort in which we considered the effect of MDD history." (PMID 27070410, 2016). "The lack of evidence from genetic studies may not negate the roles of BDNF in mood disorders." (PMID 26091093, 2015).
mood disorder (continued). "Moreover, with reference to the serum balance between brain-derived neurotrophic factor (BDNF) and its precursor pro-BDNF, an increase in circulating pro-BDNF levels was detected, but without fully clarifying whether these neurotrophins can actually be used as biomarkers of mood disorders." (PMID 33435246, 2021). "To the best of our knowledge, we believe that the present study is the first to show that serum BDNF levels before the development of MDD and other mood disorders are not low considering a history of MDE." (PMID 27070410, 2016). "Studies have also shown that inflammatory markers may discriminate between treatment-resistant and non-resistant mood disorder patients, with the augmented levels TNF-α, IL-1β, and BDNF as markers of poorer antidepressant response." (PMID 35558424, 2022). "In conclusion, this pilot study suggests that peripheral levels of BDNF and NCAM might be reduced in AUD with and without comorbid mood disorder." (PMID 32372985, 2020). "This pilot study suggests that peripheral levels of BDNF and NCAM might be reduced in AUD with and without comorbid mood disorder." (PMID 32372985, 2020).